C3 (complement C3)
Diseases named in the same sentence as C3 in open-access papers (continued):
Sharing a sentence is not in itself a finding about the gene and the disease.
cardiomyopathy (2 papers, 2021 to 2024). A disease of the heart muscle or myocardium proper. "Therefore, C3 AGT + Fibroblasts may be associated with the progression of cardiomyopathy deterioration." (PMID 38799173, 2024). "C3, a key protein in the complement system, had allotypes related to the susceptibility to CD and the development of cardiomyopathy, suggesting that PTX might act in the complement signaling pathway and reversion of C3 expression might slow down CCC progression, a matter to be further investigated." (PMID 34381739, 2021). "There are also the results of enrichment pathway by GO_BP enrichment analysis and all the differential genes of this subgroup, all three of which indicate that C3 AGT + Fibroblasts are more active for the progression of cardiomyopathy and myocardial fibrosis." (PMID 38799173, 2024). "C3 AGT + Fibroblasts exhibit increased sensitivity towards adverse outcomes in cardiomyopathy, such as myocardial fibrosis and impaired cardiac contractile function, compared to other cardiac fibroblast subpopulations." (PMID 38799173, 2024). "We hypothesized that the heterogeneity of C3 AGT + Fibroblasts in cardiomyopathy is more prominent, and the possibility exists with the development of cardiomyopathy." (PMID 38799173, 2024). "The differential cellular plasticity and transcriptional regulatory activity between C3 AGT + Fibroblasts and other subgroups offer new perspectives for targeting fibroblast subpopulation activity to treat cardiomyopathy." (PMID 38799173, 2024). "Thus, C3 AGT + Fibroblasts in the normal group had a modest correlation with other subpopulations, whereas C3 AGT + Fibroblasts after the development of cardiomyopathy lost some correlation with other subpopulations." (PMID 38799173, 2024).
cerebral infarct (2 papers, 2015 to 2024). "Inhibiting C3 activity can alleviate the inflammatory response and decrease the volume of cerebral infarction in MCAO mice." (PMID 38789486, 2024).
cerebral palsy (2 papers, 2015 to 2021). A group of disorders affecting the development of movement and posture, often accompanied by disturbances of sensation, perception, cognition, and behavior. "Notable advances from clinical data showed reduced levels of the complement component C3 in the blood of neonates who subsequently developed cerebral palsy and increased levels of peptides C3a and C5a after fetal acidosis." (PMID 33925147, 2021).
Chronic colitis (2 papers, 2019 to 2024). A chronic inflammatory disease of the large intestine (colon, cecum and rectum). "Recently, our group published results demonstrating a correlation between fecal C3 level and disease activity, as well as the opsonization of mucosa-associated bacteria with C3 cleavage fragments, in a mouse model of experimental chronic colitis." (PMID 30669641, 2019). "have proposed C3 as a potential therapeutic target to modulate intestinal immune responses in chronic colitis." (PMID 38660311, 2024).
colorectal adenocarcinoma (2 papers, 2022 to 2025). The most common type of colorectal carcinoma. "The mast cells activated were C3-associated immune cells, where the C3 gene can predict the prognosis of colorectal adenocarcinoma." (PMID 36118850, 2022). "In addition, C3 was proved to be a new immune marker for differentiating the prognosis of patients with colorectal adenocarcinoma." (PMID 40396123, 2025).
cryptococcal infection (2 papers, 2021 to 2022). "(in vivo) Cryptococcus neoformans infection model in mice (WT, C3 deficient, and C5 deficient)." (PMID 34408631, 2021).
delirium (2 papers, 2019 to 2023). A disorder characterized by confusion; inattentiveness; disorientation; illusions; hallucinations; agitation; and in some instances autonomic nervous system overactivity. "Acute phase proteins (complement c3, fibrinogen and haptoglobin) may be associated with the inflammatory process in delirium." (PMID 30797230, 2019). "CRP is commonly used clinically as a blood biomarker also in delirium and in postoperative patients or patients with multiple traumas characterized by an early complement component 3 (C3) activation, represented by plasma C3 depletion and upregulation of cleaved forms of C3 (including C3a and C3b)." (PMID 37958765, 2023).
demyelinating disease (2 papers, 2020 to 2023). A broad group of disorders that affect the myelin sheaths that cover the neurons. "Upregulation of C3, Nrp2, Lrp1 was observed in demyelinating disease." (PMID 36817487, 2023).
dermatitis herpetiformis (2 papers, 2025 to 2026). "Skin histopathology showed dermal edema with a neutrophilic infiltrate, and direct immunofluorescence revealed granular IgA and C3 deposits along the dermoepidermal junction, findings diagnostic of dermatitis herpetiformis (DH)." (PMID 42110016, 2026).
dyslipidaemia (2 papers, 2019 to 2024). "A mutation in the C3 gene could result in an increase in circulating C3 concentrations and was related to dyslipidaemia and cardiovascular disease." (PMID 31829184, 2019).
gastritis (2 papers, 2019 to 2024). Inflammation of the stomach. "Activated C3 is locally deposited in gastritis and GC lesions, and C3 deposition is negatively correlated with plasma C3 and C3a levels." (PMID 38584705, 2024).
Granuloma (2 papers, 2020 to 2024). A compact, organized collection of mature mononuclear phagocytes, which may be but is not necessarily accompanied by accessory features such as necrosis. "The C3 cleavage fragments modulate CXCR4-mediated response; TNF-α, which stimulates the production of C3, is also important in granuloma formation; and its neutralization results in the loss of granuloma structure." (PMID 32344637, 2020). "C3 (m/z = 2,217.25) was mainly expressed in the periphery of the granulomas from cattle; in accordance with the MALDI-MSI image, C3 immunolabeling was found in the cytoplasm of epithelioid macrophages and multinucleated giant cells of granulomas with lack of expression at the necrotic core." (PMID 39021575, 2024).
Hashimoto thyroiditis (2 papers, 2023 to 2024). An autoimmune disorder caused by the production of autoantibodies against thyroid tissue. "In this case, we comprehensively presented a case of SPS with co-occurring Hashimoto’s thyroiditis and an associated decrease in serum C3 complement, as well as a discussion on the current data on this topic." (PMID 39087011, 2024). "In this case, we comprehensively presented a case of SPS with co-occurring Hashimoto’s thyroiditis and an associated decrease in serum C3 complement levels as well as a discussion on the current data on this topic." (PMID 39087011, 2024). "The present case study described a patient with SPS (increased anti-GAD65 antibody in serum and cerebrospinal fluid) co-occurring Hashimoto’s thyroiditis, accompanied by a decrease in C3 complement levels." (PMID 39087011, 2024). "The present case study described an SPS patient (increased anti-GAD65 antibody in serum and cerebrospinal fluid) with co-occurring Hashimoto’s thyroiditis and decreased C3 complement levels." (PMID 39087011, 2024). "In this case, we report a patient with SPS and Hashimoto’s thyroiditis who exhibited a reduction in complement C3 levels without any underlying etiologies accounting for such a decrease." (PMID 39087011, 2024). "In other words, the decrease in C3 complement levels may also be a concurrent manifestation of Hashimoto’s thyroiditis." (PMID 39087011, 2024). "Additionally, it is important to note that complement activation plays a role in the pathogenesis of Hashimoto’s thyroiditis; therefore, we cannot definitively conclude that C3 complement alone contributes to the development of SPS." (PMID 39087011, 2024). "Given the low incidence of SPS and limited reports on its concurrent occurrence with Hashimoto’s thyroiditis, along with decreased serum C3 complement levels, there may be a gap in the clinical understanding of SPS." (PMID 39087011, 2024). "In future studies, we will deeply focus on the alterations in C3 complement levels, particularly during immunotherapy, SPS disease recurrence, and Hashimoto’s thyroiditis remission or relapse." (PMID 39087011, 2024).
hemorrhage (2 papers, 2012 to 2022). Loss of blood from the vascular compartment to the exterior or into nonvascular body space as a result of rupture or severance of the blood vessels. "Moreover, astrocytes upregulate and release C3, which binds to C3aR in microglia, promoting neuroinflammation and hydrocephalus after germinal matrix hemorrhage." (PMID 36189326, 2022).
Hypocalcemia (2 papers, 2022 to 2026). An abnormally decreased calcium concentration in the blood. "However, the levels of IgG increased significantly and complement C3 decreased obviously in the sera of SLE patients with hypocalcemia, suggesting that the low serum calcium in SLE patients may not only promote the production of autoantibodies, but also induce the more active immune response." (PMID 35757710, 2022).
idiopathic pulmonary arterial hypertension (2 papers, 2012 to 2024). A sporadic form of pulmonary arterial hypertension (PAH) characterized by elevated pulmonary arterial resistance leading to right heart failure. "The levels of C3 were found to be altered in the sera of patients with idiopathic pulmonary arterial hypertension, although the nature of this association is unclear." (PMID 22416803, 2012). "C3 has been suggested to be involved in the pathogenesis of PH, as its expression was found to be increased in the lungs of patients with idiopathic pulmonary arterial hypertension (IPAH) and hypoxia-induced PH mice." (PMID 38708342, 2024).
insulinoma (2 papers, 2024 to 2026). "Moreover, we showed that C3 participates in cytoprotective autophagy in the INS-1 rat insulinoma cell line, through its interaction with ATG16L1, and defective autophagic processes in C3–KO INS-1 cells also had increased insulin content and subsequent secretion." (PMID 41386533, 2026).
intracerebral hemorrhage (2 papers, 2019 to 2024). A cerebrovascular disorder characterized by bleeding into one or both cerebral hemispheres including the basal ganglia and the cerebral cortex. "For example, C3-/- mice display reduced inflammasome activation in an intracerebral hemorrhage (ICH) model." (PMID 30634407, 2019).
invasive breast carcinoma (2 papers, 2018 to 2020). A carcinoma that infiltrates the breast parenchyma. "Moreover, in human invasive breast cancers, C3 expression is positively correlated with expression of CAFs activation markers and functional effectors." (PMID 31931851, 2020). "In addition, hATT-CMs were also enriched in complement component 3 (C3) (20-fold change), involved in the activation of the complement system, and in vimentin and desmin (8.5-fold and 6.5 fold change), which are mesenchymal cell proteins related to an invasive breast cancer phenotype." (PMID 30123423, 2018). "To sum up, we concluded that production of C3 complement may contribute to enhancing the function of CAF and promoting the formation of invasive breast cancer." (PMID 31931851, 2020).
kidney injury (2 papers, 2022 to 2023). Trauma to the kidney. "We found that the protein SPP1, C3 and HAVCR1 might also play critical roles in the ER stress and phagocytosis in the CaOx crystal formation process and its related kidney injury." (PMID 36932340, 2023). "While lower platelet counts correlated with kidney injury in the PR3-ANCA subgroup (eGFR loss: p=0.0272), we did not observe an independent association with complement C3 levels (p=0.4497)." (PMID 36439156, 2022).
Listeria infection (2 papers, 2021 to 2025). "C3 also plays a role in adaptive immunity, being required for efficient T cell activation during murine listeriosis." (PMID 34858876, 2021). "For instance, blocking the functional activity of C3 through the use of an anti-CR3 antibody inhibits neutrophil recruitment to Listeria infection foci and reduces liver tissue damage." (PMID 34858876, 2021). "Eight of these genes were similarly inhibited by Listeria infection in PMH: they encode (i) the activating enzyme C1S of the C1 complex, (ii) the central component C3, (iii) the membrane-attack proteins C6 and C8A, and (iv) four complement regulators (C1QTNF6, CFH, CFHR2, VTN)." (PMID 34858876, 2021).
lymphedema (2 papers, 2022 to 2023). Excess fluid collection in tissues, causing swelling. "As such, c3 may represent interstitial progenitor cells closely associated with the fibrosis of adipose tissues in lymphedema." (PMID 35725971, 2022). "More CD4+ T cells infiltrated around lymphatic vessels and throughout lymphedema regions of C3 KO mice compared with wild-type mice." (PMID 37940849, 2023). "To examine the activation of the complement system in lymphedema formation, we analyzed the expression of C3 in the tissue of tail lymphedema on POD21 using real-time RT-PCR and fluorescent immunohistochemistry." (PMID 37940849, 2023). "In the present study, C3 was shown to be transcriptionally upregulated in the mouse tail lymphedema model and C3, as well as C4, was shown to be detected around the dilated lymph vessels." (PMID 37940849, 2023). "C4 was co-localized with C3 around the dilated lymphatic vessels, suggesting that the classical or lectin pathway should be activated in the lymphedema region of the mouse tail model." (PMID 37940849, 2023). "More cells, including immune cells, accumulated in lymphedema tissues of C3 KO and C5 KO mice than in wild-type mice." (PMID 37940849, 2023). "Our mouse tail lymphedema models showed increased expression of C3, and that the classical or lectin pathway was locally activated." (PMID 37940849, 2023). "In the present study, an increased number of dead cells was detected in the lymphedema region of C3 KO mice compared with that of wild-type mice." (PMID 37940849, 2023). "Activation of the complement pathways was observed in lymphedema tissue, so we compared the extent of lymphedema swelling in C3 KO mice and C5 KO mice with that in wild-type mice." (PMID 37940849, 2023). "The presence of c1, c3, and c5 cells was also confirmed by immunofluorescence staining in the subcutaneous adipose tissue sections from lymphedema patients and healthy donors." (PMID 35725971, 2022). "Among them, the PRG4+/CLEC3B+ ASC subpopulation c3 was significantly expanded in lymphedema and related to adipose tissue fibrosis." (PMID 35725971, 2022). "Interestingly, more immune cells seemed to infiltrate the lymphedema region in both C3 KO and C5 KO mice compared with in wild-type mice." (PMID 37940849, 2023). "Augmented expression of C3 transcript was detected in the tissue of tail lymphedema." (PMID 37940849, 2023). "In the present study, we analyzed whether complement activation is involved in the development of lymphedema using C3 knockout (KO) mice and C5 KO mice." (PMID 37940849, 2023). "In addition, C3 proteins were distributed around the dilated lymphatic vessels in lymphedema tissue." (PMID 37940849, 2023). "Furthermore, we pinpointed the ASC subpopulation that was closely associated with the pathophysiology of lymphedema, i.e., c3 (PRG4+/CLEC3B+ ASCs), which was significantly expanded in lymphedema." (PMID 35725971, 2022). "No prominent augmentation of edematous swelling was observed in C3 KO mouse tails, but there was a significant increase in infiltration of CD4+ T cells in the lymphedema tissues." (PMID 37940849, 2023). "We detected increased infiltration of both F4/80+ macrophage cells and Ly6G+ granulocyte cells into lymphedema tissues of some of C3 KO and C5 KO mice, but the change was not significant." (PMID 37940849, 2023). "In some C3 KO and C5 KO mice, macrophages and granulocytes were not significantly increased in the lymphedema region, possibly because there was little or no production of C3a and C5a." (PMID 37940849, 2023).
macrophage activation syndrome (2 papers, 2021 to 2025). A complication of rheumatic disease that is caused by excessive activation and uncontrolled proliferation of T lymphocytes and well-differentiated macrophages. "An auto-immune panel (antinuclear antibody, anti-DNA, C3, C4, c-antineutrophil cytoplasmic antibody, p-antineutrophil cytoplasmic antibody, antiphospholipid antibodies, lupus anticoagulant, and anti-cardiolipin antibodies) was done to rule out macrophage activation syndrome (MAS)." (PMID 39897279, 2025).
MALT lymphoma (2 papers, 2017 to 2024). An indolent, extranodal type of non-Hodgkin lymphoma composed of small B-lymphocytes (centrocyte-like cells). "A patient diagnosed with MALT lymphoma displayed increased levels of C3, C4, rheumatoid factor, anti-SSA/SSB antibodies, anti-Scl-70 antibodies, and anti-Ro-52 antibodies." (PMID 38959275, 2024).
melancholic depression (2 papers, 2016 to 2020). "The study demonstrated that in atypical depression the following molecules were altered as compared to melancholic depression: higher leptin, FABPa, complement C3, insulin, B2-microglobulin, ACE, and lower insulin-like growth factor-binding protein 1 and 2 (IGFBP1, IGFBP2) and mesothelin." (PMID 33255237, 2020).
microscopic polyangiitis (2 papers, 2018 to 2024). Microscopic polyangiitis (MPA) is an inflammatory, necrotizing, systemic vasculitis that affects predominantly small vessels (i.e. small arteries, arterioles, capillaries, venules) in multiple organs. "The study showed that low serum C3 levels and high serum C4 levels were associated with a higher risk of poor renal prognosis in patients with microscopic polyangiitis." (PMID 39588186, 2024).
mood disorder (2 papers, 2023 to 2025). A cognitive disorder a disturbance in which the person's mood is hypothesized to be the main underlying feature. "This study is recognized for being the first in Indonesia to examine the connection between mood disorders and complement levels C3 and C4 utilizing HADS." (PMID 37884917, 2023).
muscle ache (2 papers, 2020 to 2023). "The risk factors for death included dyspnoea, muscle ache, elevated myocardial enzymes, elevated C3 in over-70 patients and dyspnoea, pharyngalgia, chronic cardiac disease, increased CRP, IgA, decreased platelets in under-70 patients." (PMID 33106442, 2020).
muscular dystrophy (2 papers, 2008 to 2011). Muscular dystrophy (MD) refers to a group of more than 30 genetic diseases characterized by progressive weakness and degeneration of the skeletal muscles that control movement. "C1S, C3 and C1QA genes, involved in complement mediated immunity contributing to muscular dystrophy, also showed heterogeneous expression across the dystrophy samples, with corresponding changes in tm-scores." (PMID 21453538, 2011).
myocardial ischemia (2 papers, 2023 to 2024). A disorder of cardiac function caused by insufficient blood flow to the muscle tissue of the heart. "A study found that degenerative necrotic tissue cells after myocardial ischemia were enriched in the complement and coagulation cascade pathway, and complement system activation products such as C3, C4, and C5 played a major role in myocardial ischemia-reperfusion inflammatory injury." (PMID 37965086, 2023).
optic neuritis (2 papers, 2019 to 2024). Optic neuritis is inflammation of the optic nerve, the nerve that carries the visual signal from the eye to the brain.The conditionmay cause sudden, reduced vision in the affected eye(s). "Whether a similar complement-dependent intercellular cross talk (C3-C3aR) may be involved in defective debri clearance and inefficient remyelination in optic neuritis warrants further investigation." (PMID 31292459, 2019). "Regardless of the etiology of the sex difference, the evidence that C3 expressing astrocytes in optic nerve are found more in females than in males suggests that a treatment targeting expression of C3 in astrocytes during optic neuritis may be more effective in females than in males." (PMID 31292459, 2019). "Together, these data revealed that during optic neuritis, astrocytes in ON undergo important molecular changes, characterized by upregulation of THBS1 in early EAE, and upregulation of C3, in late EAE." (PMID 31292459, 2019).